KRAS (KRas proto-oncogene, GTPase)
Diseases named in the same sentence as KRAS in open-access papers (continued):
Sharing a sentence is not in itself a finding about the gene and the disease.
pancreatic cancer (continued). "For instance, KRAS is identified as the most frequently mutated oncogene in more than 90% of pancreatic cancer patients, and the constitutively active KRASG12D mutation has been proved to facilitate the formation of pancreatic intraepithelial neoplasia." (PMID 34023857, 2021). "In this regard, persistent genetic mutations are the hallmark of pancreatic cancer, and mutations in KRAS occur in most PDACs." (PMID 33946266, 2021). "Pancreatic cancer arises from activating mutations in oncogenic Kras, and the majority (90%) of human pancreatic tumors develop sporadically from cells carrying KRAS mutations;20 however, KRasG12D mutations alone are insufficient to drive malignancy." (PMID 33891893, 2021). "Pancreatic carcinoma (PC) is greatly induced by the KRAS gene mutation, but effective targeted delivery for gene therapy has not existed." (PMID 34575504, 2021). "Earlier reports were concordant with KRAS activation mutation and highly significantly associated with the development of metastasis pancreatic carcinoma." (PMID 34575504, 2021). "KRas has been shown to be required for sustained tumorigenic growth in advanced pancreatic carcinoma, with loss of KRas expression leading to tumor regression." (PMID 34680208, 2021). "Our study showed that in the subgroup analysis for pancreatic cancer, the KRAS was the most mutated gene (58% (95% CI: 31–83%)) and MAPK was the most altered pathway (31% (95% CI: 5–66%))." (PMID 33127962, 2020). "Pancreatic tumor tissue collected from NSG mice orthotopically transplanted with patient-derived organoids also expressed KRAS mutation and PD-L1 consistent with the patient’s organoid culture and tumor tissue." (PMID 33348809, 2020). "KRAS is mutated in the majority of pancreatic cancer patients, and the mutation contributes to the aggressive phenotype of the disease." (PMID 32326109, 2020). "In TCGA PAAD datasets, 70% pancreatic cancer patients with KRAS mutations were un-responsive to cancer therapy, while, 49% patients without KRAS mutations were un-responsive to cancer therapy." (PMID 32950968, 2020). "KRAS mutations have been reported to be poor prognostic markers in colorectal, lung, and pancreatic cancer." (PMID 33207545, 2020). "In pancreatic cancer, high ctDNA levels of KRAS and/or other mutations have been associated with poor progression-free survival (PFS) and/or OS." (PMID 32010431, 2020). "KRAS, a kind of small GTPase, is persistently activated upon mutation in pancreatic cancer and continuously stimulates downstream effectors (e.g., PI3K and RAF)." (PMID 32122374, 2020). "At this time, even with advanced sequencing technology, the identification of KRAS mutations in cfDNA exhibits limited sensitivity as an early detection marker for pancreatic cancer." (PMID 32707720, 2020). "A recent study demonstrated that ART selectively induced ferroptosis in pancreatic cancer cells carrying a mutation in the KRAS gene." (PMID 33316936, 2020). "KRAS mutation is an initiating and driver gene during pancreatic cancer development and is found to mutate the most frequently in over 90% PDAC cases." (PMID 33117704, 2020). "Next, we examined the power of a combination of five marker genes and KRAS mutations in a larger sample size of pancreatic cancers using a public database." (PMID 32520974, 2020).
pancreatic cancer (continued). "KRAS mutations drive over 90% of pancreatic cancer, a disease with a dismal overall 5-year survival rate of only 9%1." (PMID 32499547, 2020). "Pancreatic cancer is characterized by the expression of oncogenic KRAS, and >90% of the patients with pancreatic cancer have oncogenic mutations in the KRAS." (PMID 32978257, 2020). "A recent study reported that tumor-derived KRAS mutations in pancreatic cancer are predominantly carried by short and ultra-short cfDNA fragments." (PMID 32630266, 2020). "In a mouse model of genetically induced pancreatic cancer, activating KRAS mutations induces the differentiation of acinar cells to duct-like cells and progression to PanIN." (PMID 32891173, 2020). "Corresponding to the higher un-responsiveness of pancreatic cancer patients with KRAS mutation or CDKN2A deletion, we found that MMP14 and PKM2 were highly expressed in drug un-responsive patients." (PMID 32950968, 2020). "Mutations in these genes are the most commonly encountered mutations in the majority of patients with pancreatic cancer, although potential therapeutic-target genes are limited to KRAS G12C and CDKN2A, which are found only in a small subgroup of patients." (PMID 31997007, 2020). "Taken together, we defined the diagnostic criterion for pancreatic cancer as KRAS mutation positive, and/or DNA methylation positive in at least one marker gene in cfDNA samples." (PMID 32520974, 2020). "Tumor cells with a high prevalence of KRAS activating mutations, like pancreatic cancer, have the distinction of a poor prognosis." (PMID 32655498, 2020). "Nevertheless, literature data also reported that driver mutations in both GNAS and KRAS co-occur in a subset of pancreatic cancer patients." (PMID 33266496, 2020). "Among studied genes, KRAS in GC and pancreatic cancer and APC in CRC had the most association with cancer outcome." (PMID 33127962, 2020). "Here, in a mouse model of mutant KRAS-driven pancreatic cancer, loss of AGO2 allows precursor lesion (PanIN) formation yet prevents progression to pancreatic ductal adenocarcinoma (PDAC)." (PMID 32499547, 2020). "With a focus on pancreatic cancer, there are evidence of its convergence in downstream pathways implicated in major genetic alterations found in pancreatic cancer, primarily KRAS." (PMID 32010971, 2020). "In previous studies, we found that VMP1 expression is induced by mutated KRAS in pancreatic tumor cells." (PMID 32655498, 2020).
pancreatic cancer (continued). "In humans, nearly 90% of pancreatic cancer patients show mutations in KRAS (cBioportal), and our autochthonous models were based on mutations in KRAS or in upstream signaling receptors (EGFR)." (PMID 31940491, 2020). "We found that heterozygous loss of BAP1—but rarely mutation—occurs in over a quarter of PDAs and 40% of acinar cell carcinomas (ACCs), a rare and distinct subtype of pancreatic cancer that infrequently harbors KRAS mutations." (PMID 32541668, 2020). "When DNA methylation markers were combined with the KRAS mutation status (diagnosed as pancreatic cancer when KRAS mutation positive or/and DNA methylation positive in at least one marker gene), the sensitivity was further improved to 98%." (PMID 32520974, 2020). "Such an analysis of KRAS mutations in pancreatic cancer identified that the G12R mutation has the highest selective advantage." (PMID 32725342, 2020). "We had to wait until 1994 for the discovery of the presence of a KRAS mutation in the cfDNA extracted from plasma of patients with pancreatic cancer." (PMID 37361495, 2020). "Kimple and colleagues showed that KRAS mutation confers resistance to radiation in pancreatic cancer cells likely due to failure to downregulate Akt phosphorylation." (PMID 33228205, 2020). "In this model, pancreatic cancer arises from multiple genetic alterations, starting with mutations that promote the constitutive activation of KRAS (Kirsten Rat Sarcoma)." (PMID 33014438, 2020). "KRAS is one of the most commonly mutated oncogenes in human cancer and is a key oncogenic driver in many lung and most pancreatic cancers." (PMID 31874105, 2020). "KRAS mutations have been validated in most pancreatic preinvasive lesions, and they are considered an initiating step in the pathogenesis of pancreatic neoplasms." (PMID 32934653, 2020). "For example, TRAILR2 expression is associated with poor prognosis in pancreatic cancer and KRAS mutated colon cancer." (PMID 32433558, 2020). "Conversely, in pancreatic cancer cells, KRAS mutation downregulates GLUD activity and upregulates the aspartate synthase (GOT1) enzyme to provide NADPH for the proper maintenance of redox homeostasis." (PMID 33081387, 2020). "KRAS is the most frequently mutated gene in PDA, and KRAS mutations are found in 95% of pancreatic cancers." (PMID 33396954, 2020). "A significant portion of tumors harbors mutations in KRAS, with KRAS-G12D being the most common in pancreatic cancers." (PMID 33298945, 2020).
pancreatic cancer (continued). "Mutations of KRAS have been found in over 95% of pancreatic ductal adenocarcinomas and are considered as a potential biomarker for patients with pancreatic cancer." (PMID 32764295, 2020). "We have previously shown that NK functional inactivation and loss of numbers occurs at both the pre-neoplastic and neoplastic stages of pancreatic cancer due to the effects of both the KRAS mutation and high fat calorie diet." (PMID 33230147, 2020). "Engineered EV have also been used to directly and specifically target the mutated form of the GTPase KRAS, a key driver of pancreatic cancers." (PMID 32942702, 2020). "There is a discrepancy between the high rates of KRAS mutations in pancreatic cancer by comparing the COSMIC database and individual large cohort reports." (PMID 32725342, 2020). "At first, we examined the genome-wide DNA methylation status of 37 FNA pancreatic cancer tissues with KRAS mutations using an Illumina Infinium HM450 Beadchip." (PMID 32520974, 2020). "Activating mutations of KRAS appear early in pancreatic cancer development and were shown to be induced by high glucose concentration, this discovery being instrumental in the better understanding of why diabetes support PDAC initiation." (PMID 32756381, 2020). "Alternately, we identified a subpopulation with differential response to selumetinib for a small proportion of KRAS NSCLC cell lines, but this subpopulation contained a higher proportion of colorectal and pancreatic cancer cells with KRAS mutations." (PMID 31602313, 2019). "We observe that exosomes from pancreatic cancer cell lines, independently from the KRAS mutation status, can initiate the transformation of NIH/3T3 cells, while exosomes from normal pancreatic cells do not possess this ability." (PMID 31134894, 2019). "Located on chromosome 12, the KRAS gene codes for the 21 kDa GTPase KRAS and is mutated in over 90% of pancreatic cancers." (PMID 31608239, 2019). "It is notable that in spite of KRAS activation by gene mutation in 90% of the cases in pancreatic cancer, various miRNAs capable of directly targeting KRAS are simultaneously downregulated." (PMID 31612113, 2019). "For example, KRAS mutation is present in more than 90% of pancreatic cancer cases and controls both tumorigenesis and metabolic reprogramming." (PMID 30967773, 2019). "KRAS mutation has been confirmed to be one of the earliest genetic changes in pancreatic carcinogenesis and has been observed in more than 90% of pancreatic cancers." (PMID 30347501, 2019). "The vast majority of KRAS mutations in pancreatic cancer are gain-of-function mutations, most of which occur in codon 12 with substitution of the Glycine for Aspartate (G12D)." (PMID 31470511, 2019). "As the most commonly mutated gene in pancreatic cancer, detection of mutated KRAS in ctDNA is a highly studied area." (PMID 31608239, 2019). "KRAS mutation has been reported to be the driving force for pancreatic cancer oncogenesis and progression." (PMID 31889908, 2019). "In the GSE79668 and TCGA RNA-seq datasets, KRAS mutations were observed in 82.4% of all pancreatic tumour cases." (PMID 31703415, 2019). "The activation of ERK1/2 has been demonstrated to play a crucial role in the TGF-β dependent malignant transformation of pancreatic cancer; this is because KRAS mutations and altered TGF-β signalling are frequent in pancreatic cancer." (PMID 30866547, 2019).
pancreatic cancer (continued). "KRAS mutations are the most commonly used targets for ctDNA analysis as they are present in 90–95% of pancreatic cancer." (PMID 31323810, 2019). "Several studies previously reported that the presence of detectable ctDNA was associated with poor survival in pancreatic cancer or that the presence of KRAS alterations in ctDNA was a poor prognostic marker for OS in advanced PDAC." (PMID 31801585, 2019). "Lastly, downregulation or loss of Let 7 family miRNAs in pancreatic cancer cells leads to the overexpression of KRAS, as these miRNAs negatively regulate the expression of KRAS by binding to its 3′ UTR region." (PMID 31557962, 2019). "They concluded that the combination of mutated KRAS-targeting siRNAs and chemotherapy is well tolerated, safe, and demonstrated potential efficacy in pancreatic cancer patients." (PMID 31470511, 2019). "The KRAS mutation is a primary trigger in >90% of cases of pancreatic cancer progression, and contains a nuclear-hypersensitive element (NHE)." (PMID 31284594, 2019). "Oncogenic KRAS mutation, an early event in the development of pancreatic cancer, is involved in over 90% of pancreatic cancer cases." (PMID 31284594, 2019). "Previous mutational analyses have shown that KRAS mutations are commonly detected in pancreatic juice sampled from patients with pancreatic cancer or from persons undergoing screening because they are considered high-risk subjects." (PMID 30611220, 2019). "Many studies showed that IPMN and pancreatic cancer have the same somatic mutations, such as in KRAS and GNAS." (PMID 31338331, 2019). "We next evaluated the effects of ORP8 knockdown on KRAS and PtdSer localization in a panel of pancreatic cancer cell lines that are wild-type for KRAS, such as BxPC-3, or contain a KRAS mutation, such as PANC-1, MiaPaCa-2, and MOH." (PMID 31451509, 2019). "Loss of expression of both activating and inhibitory NK cell ligands was also seen on osteoclasts from KC mice with pancreatic KRAS mutation correlating with the loss of NK cell function and generation of pancreatic tumors." (PMID 31878338, 2019). "Pancreatic cancer constitutes a genetic disease in which somatic mutations in the KRAS proto-oncogene are detected in 95% of cases." (PMID 31231585, 2019). "The overexpression of HDAC1 and mutant KRAS were known to cause proliferation of pancreatic cancer cells, and therefore silencing the two genes was used as an anti-cancer strategy in this study." (PMID 32038249, 2019). "A literature search for relevant studies using the search terms “circulating DNA” and “pancreatic cancer” was conducted in PubMed, and 18 studies investigating KRAS-mutated ctDNA in patients with PDAC were identified." (PMID 31891652, 2019). "Further workup revealed that circulating tumor‐derived DNA and liver metastases originated from a synchronous KRAS‐mutated cancer of the pancreas." (PMID 31134762, 2019). "Among them, KRAS mutations (G12D, G12V, G12C, G12R, and G13D) are present at high frequencies in various cancer types including lung, colon, and pancreatic cancers." (PMID 30813491, 2019). "Both Charoentong and Witkiewicz have reported the high frequency of the KRAS G12D mutation in pancreatic cancer." (PMID 31781598, 2019). "Given that activating KRAS mutations are the most prevalent oncogenic driver in pancreatic cancer 32, we investigated the role of KRAS in the regulation of PAI-1 expression." (PMID 31695760, 2019). "Whilst ER expression was only prognostic in the subgroup of women with pancreatic cancer in unadjusted analysis, stromal PR positivity conferred a contrasting prognostic value dependent on KRAS mutation status in the entire cohort, and in particular in women." (PMID 31827798, 2019).